TYRO3 (TYRO3 protein tyrosine kinase)
Diseases named in the same sentence as TYRO3 in open-access papers (continued):
Sharing a sentence is not in itself a finding about the gene and the disease.
breast carcinoma (continued). "We found nominal evidence of association with breast cancer overall for LoF variants in three genes (ZFAND1, TMEM206/PACC1, and TYRO3), with ER-negative breast cancer in two genes, DNAH11 and PARP2, and with ER-positive disease in four genes LAMC3, MTMR11, EPN3, and SLC22A10." (PMID 35884425, 2022). "Interestingly, downregulation of TYRO3 in various breast cancer cell lines resulted in cell-specific responses to signaling pathways." (PMID 34721022, 2021). "High levels of TYRO3 expression correlated with poor response to therapy in patients with HER2-positive breast cancer and exogenous expression of TYRO3 was sufficient to confer resistance to the small molecule HER2 inhibitor lapatinib in 2 of 3 breast cancer cell lines." (PMID 30501104, 2018). "Moreover, it plays a role in a Tyro3/Axl autocrine signaling circuit to sustain malignancy in thyroid carcinoma and is important for proliferation in breast cancer." (PMID 27486820, 2016). "We utilized a syngeneic mouse model of bone metastasis by using the EO771 breast cancer cell line in mice harboring a conditional deletion of MERTK and TYRO3 in osteoblasts (Col1a1-2,3kb-cre+Mertkflox/flox and Col1a1-2,3kb-cre+Tyro3flox/flox)." (PMID 38203403, 2023). "In a later publication using a tyrosine antibody array, several RTKs able to bind to PKM2 were detected, and their ability to phosphorylate PKM2 was confirmed when overexpressed in a breast cancer cell line (Axl, EpHA2, FAK, Tyro3, ErbB2, 29440169)." (PMID 35054968, 2022). "AXL, a member of the TYRO-3, AXL and MER (TAM) subfamily, is, today, considered a predictive and prognostic biomarker in many tumor contexts, primarily breast cancer." (PMID 33182542, 2020). "Prolonged treatment of breast cancer with IGF1R TKIs has also been observed to promote resistance via activation of an alternate RTK, TYRO3." (PMID 30653502, 2019). "Using the TCGA database for breast cancer patients (cBioPortal, PanCancer Atlas), we also showed that CDK6 expression significantly correlates with the expression of Met and the TAM RTKs, Axl, MerTK, and Tyro3, and is inversely correlated with HER2." (PMID 38927958, 2024). "Furthermore, inhibition of TYRO3 by siRNA or shRNA in hepatocellular carcinoma, CRC, and breast cancer cell lines directly reduce PI3K/AKT phosphorylation." (PMID 34721022, 2021). "Moreover, treatment with a PI3K inhibitor abrogated transformation in NIH3T3 cells expressing a chimeric EGFR-TYRO3 protein and reversed TYRO3-dependent chemoresistance in MCF10A breast cancer cells, implicating PI3K as a critical downstream effector of TYRO3 oncogenic activity." (PMID 30501104, 2018).
ZIKV infection (18 papers, 2016 to 2025). "Overall, an assessment of the early timepoint of ZIKV infection in the SH-SY5Y cells revealed upregulation of Tyro3 and MER-TK at 2 h and downregulation at 48 h post infection." (PMID 41373653, 2025). "The overexpression of Mertk and AXL, and the downregulation of Tyro-3 suggest that these are receptors that promote ZIKV infection in our culture." (PMID 36989308, 2023). "In placental cell cultures and chorionic villi explants, susceptibility to ZIKV infection is mediated via AXL, TYRO3, and TIM1." (PMID 38137537, 2023). "Also, we found that ZIKV infection modulates the expression of type 1 interferons (IFNs) and entry receptors such as Tyro3, Axl, and MER-TK (TAM)." (PMID 41373653, 2025). "On the other hands, we found that ZIKV infection decreases tyro-3 expression." (PMID 36989308, 2023). "These receptors include TAM family proteins (tyrosine kinases) such as Tyro3, Axl, and Mertk; TIM1, an immunoglobulin produced by T cells; and DC-SIGN proteins on fibroblasts, which allowed the different cells to be susceptible to ZIKV infection." (PMID 36558744, 2022). "ZIKV infection of Sertoli cells was dependent on the TAM (Tyro3, Axl, and Mer) family receptor Axl." (PMID 29615760, 2018). "Previous studies have shown that AXL and CD209 are ZIKV receptors, and in skin cells, AXL is much more efficient than CD209, TYRO3, and TIM in promoting ZIKV infection (24, 26, 52, –, 54)." (PMID 39570015, 2024). "We analyzed the expression of Tyro-3, AXL, and Mertk basally and upon ZIKV infection in our hNS1-derived astrocyte cultures." (PMID 36989308, 2023). "In human pluripotent stem cells (hPSC)-derived microglia, ZIKV infection induced the differential expression of AXL, TYRO3, MERKT, and TIM." (PMID 38137537, 2023). "The TAM receptors Tyro3 and AXL, candidate receptors for Zika virus infection, are also expressed on moDCs." (PMID 36949942, 2023). "To explore the role of these potential host factors in ZIKV infection of hTSCs, STBTS and EVTTS, we compared the expression of AXL, TYRO3, MERTK and TIM-1 in hTSCs, STBTS and EVTTS by qRT-PCR." (PMID 37684223, 2023). "Type II IFN (IFNγ) are key inducers of proinflammatory cytokines such as IRF1, IFIT1, CXCL10 and crucially, known cellular receptors for ZIKV infection such as AXL, Tyro3, and DC-SIGN." (PMID 35536870, 2022). "Several entry receptors including the innate immune receptor DC-SIGN, transmembrane protein TIM-1 and TAM receptors (TYRO3, AXL, MER), have been shown to facilitate entry and enhance ZIKV infection." (PMID 30319635, 2018). "However, all the TAM receptors (Tyro-3, AXL, and MER-TK) showed significant (p < 0.05) downregulation in the murine cortical neurons at 72 h post ZIKV infection when compared to their respective uninfected control group of cortical neurons." (PMID 41373653, 2025). "We identify AXL as the top hit in a CRISPR/Cas9 genome-wide screen in human glioblastoma cells and establish a definitive role of AXL, but not TYRO3 or MerTK, for ZIKV infection." (PMID 40062839, 2025). "Cell surface molecules of potential importance for ZIKV infection include the C-type lectin receptors CD209 (DC-SIGN), CLEC5a and mannose receptor (MR) and the phosphatidyl serine receptors T-cell immunoglobulin and mucin domain (TIM)-1 and TAM receptors Tyro3 and AXL42–45." (PMID 31289325, 2019). "However, the role of AXL, variation in the expression of AXL and TYRO3 in pregnant women and whether TIM-1 is the sole receptor for ZIKV infection of the placenta need further study." (PMID 30319635, 2018). "While anti-Axl antibody strongly reduced ZIKV infection, antibodies targeting other receptors (TIM1, TIM4, Mer and Tyro3) did not significantly affect viral replication." (PMID 29615760, 2018).
colorectal cancer (10 papers, 2016 to 2024). A primary or metastatic malignant neoplasm that affects the colon or rectum. "In colorectal cancer, nuclear TYRO3 phosphorylated the epigenetic regulator BRD3 to regulate genes involved in colorectal cancer metastasis." (PMID 39062902, 2024). "Higher levels of TYRO3 expression correlated with worse overall survival in patients with colorectal cancer in two independent data sets and in patients with hepatocellular carcinoma." (PMID 30501104, 2018). "TYRO3 was also expressed in liver metastases in patients with colorectal cancer and in metastatic bone lesions in mice with a prostate cancer xenograft." (PMID 30501104, 2018). "Inhibition of TYRO3 in hepatocellular and colorectal carcinoma cell lines using siRNA decreased both migration and invasion in trans-well and/or scratch-wound assays." (PMID 30501104, 2018). "Collectively, these data suggest a potential role for Gas6/TAM receptor (especially Tyro3) signaling in colorectal cancer and metastasis progression." (PMID 27486820, 2016). "However, regarding expression and activation of TYRO3 a pro‐tumorigenic role in several cancer entities including colorectal cancer has been reported." (PMID 39425449, 2024). "Similarly, microRNA7 inhibits Tyro3 expression and is being examined as an RNA-based therapeutic for treating aberrant Tyro3 overexpression in human colorectal carcinoma." (PMID 39684449, 2024). "Similarly, shRNA-mediated TYRO3 inhibition in the HCT-116 and HT-29 colorectal cancer cell lines decreased migration and invasion and overexpression of TYRO3 in HT-29 cells was sufficient to enhance migration." (PMID 30501104, 2018). "Overexpression of miR-7 in hepatocellular and colorectal carcinoma cells significantly decreased TYRO3 mRNA and protein levels, and miR-7 seed sequences in the 3′ untranslated region of the TYRO3 gene were essential for miR-7 regulation of luciferase from a TYRO3 reporter construct." (PMID 30501104, 2018). "Interestingly, a recent study found that TYRO3 amounts positively correlated with colorectal cancer progression." (PMID 28727830, 2017). "Here we show that AXL, but not MERTK or TYRO3 expression is enhanced in late stage colorectal cancer (CRC) and AXL expression associates with a cell migration gene signature." (PMID 28727830, 2017). "In addition, TYRO3 and AXL co-immunoprecipitated from cell lysates derived from Rat2 cells with exogenous TYRO3 expression and from a gonadotropin-releasing hormone (GnRH) expressing neuronal cell line, and human glioblastoma and colorectal cancer cell lines expressing endogenous TYRO3 and AXL." (PMID 30501104, 2018). "A similar RTK distribution has already been reported for TYRO3 and AXL in human colorectal cancer and pancreatic cancer, respectively." (PMID 30765874, 2019). "Treatment with a neutralizing TYRO3 antibody was sufficient to induce apoptosis in cultures of the HCT-116 colorectal cancer line and colorectal cancer patient samples." (PMID 30501104, 2018). "Similarly, HCT-116 colorectal cancer cells expressing siTYRO3 were more sensitive to treatment with 5-fluorouracil and induction of apoptosis in response to 5-fluorouracil, paclitaxel, or oxaliplatin was significantly increased in cultures treated with an anti-TYRO3 antibody." (PMID 30501104, 2018). "A humanized antibody has also been described and extensive preclinical studies demonstrated reversal of TYRO3-dependent EMT phenotypes, induction of cell death, and increased sensitivity to cytotoxic chemotherapies in colorectal cancer cell lines and/or patient samples treated with the antibody." (PMID 30501104, 2018). "In addition, we identified several variants in genes not typically included in relevant gene panels for colorectal cancer, including CFTR, PABPC1 and TYRO3, which may be associated with an increased risk for cancer." (PMID 37296477, 2023).
prostate carcinoma (10 papers, 2012 to 2023). A carcinoma that arises from epithelial cells of the prostate gland. "Gas6 binds to receptor tyrosine kinases: Tyro3, MerTK, and Axl, of which the expression of the latter in prostate cancer cells is associated with increased tumor grade and bone metastasis but not lymph node metastasis." (PMID 29642534, 2018). "TYRO3 levels were elevated in serum from patients with prostate cancer or hepatocellular carcinoma, implicating TYRO3 as a potential biomarker." (PMID 30501104, 2018). "In mouse models of human prostate cancer, Axl expression is increased in DTCs compared to the primary tumor, where Tyro3 expression prevails." (PMID 25344858, 2014). "Tyro3, Axl, and MerTK mediate efferocytosis by macrophages, but their role in prostate cancer cell efferocytosis is unknown." (PMID 37644281, 2023). "Interestingly, one study suggests that the balance between AXL and TYRO-3 expression is important in the dormancy of prostate cancer cells, with high TYRO-3 levels promoting proliferation and high AXL expression leading to a quiescent phenotype." (PMID 28251492, 2017). "A recent study in which Axl expression was enhanced over that of Tyro3 and Mer showed a modest suppression of cell proliferation in prostate carcinoma cell lines and this reduction could in turn be blocked by ERK1/2 inhibitors a finding that differed from an earlier study." (PMID 22606290, 2012). "Recent work has shown that prostate cancer (PCa) cell lines express the growth-arrest specific 6 (GAS6) receptors Axl, Tyro3, and Mer, and become growth arrested in response to GAS6." (PMID 23637920, 2013). "Interestingly, prostate cancer cells express a repertoire of GAS6 receptors (including AXL, MER and TYRO3), a balanced expression of which has been shown to control dormancy (AXL) or proliferation (TYRO3)." (PMID 34831167, 2021).
colon cancer (8 papers, 2017 to 2023). "In the early stage of colon cancer, TYRO3 overexpression is associated with cancer development, as its aberrant expression promotes tumorigenesis." (PMID 34721022, 2021). "We propose G-749 as a new therapeutic agent for the treatment of colon cancer caused by abnormal TYRO3 expression or activity." (PMID 34721022, 2021). "In our study, G-749 significantly reduced the viability of colon cancer cell lines in a concentration-dependent manner and promoted the degradation of TYRO3 protein through the regulated intramembrane proteolysis (RIP) process." (PMID 34721022, 2021). "Tyrosine-protein kinase receptor TYRO3 is overexpressed in the early stage of colon cancer development and aberrant expression of TYRO3 promotes tumourigenesis and induces EMT through the regulation of SNAI1." (PMID 34003341, 2021). "When colon cancer cells were transfected with siRNA targeting TYRO3, AXL, MER, or NC, it was found that the cleaved form of poly (ADP-ribose) polymerase (PARP) and caspase 3 were significantly increased." (PMID 34721022, 2021). "When crystal violet staining was performed after down-regulating TAM RTKs in colon cancer cells, we found that the number of cells in the TYRO3-downregulated group was significantly reduced compared to the MER- and AXL-downregulated groups." (PMID 34721022, 2021). "Despite the potential for excellent anticancer effects of G-749 in colon cancer, there is a potential for on-target toxicity for the use of TYRO3 as a targeting drug." (PMID 34721022, 2021). "Blocking TYRO3 signaling by human anti-TYRO3 antibody ameliorates cancer malignancy and increased sensitivity to paclitaxel, oxaliplatin and 5-fluorouracil in different colon cancer cell lines." (PMID 34003341, 2021). "When colon cancer cell lines were treated with G-749 at various concentrations for 12 h, the total TYRO3 (110, 130 kDa) protein levels were significantly decreased, whereas TYRO3 CTF (49 kDa) levels were markedly increased in a concentration-dependent manner." (PMID 34721022, 2021). "Evidence has also supported the notion that aberrant expression of TYRO3 contributed to tumorigenesis and metastasis in colon cancer, suggesting TYRO3 as a drug target in cancer therapy." (PMID 32018224, 2020). "In colon cancer cells, C-W Chien also observed that high expression of TYRO3 could enhance tumor proliferation and migration." (PMID 37116196, 2023). "Consequently, we propose the potential of G-749 as a novel anticancer drug targeting TYRO3 in colon cancer." (PMID 34721022, 2021). "TYRO3 is overexpressed in polyp and colon cancers, but is rarely expressed in normal tissues." (PMID 34721022, 2021). "Furthermore, in a recent study using TYRO3 antibodies for the treatment of colon cancer, TYRO3 inhibited epithelial-mesenchymal transition (EMT) in colon cancer cells." (PMID 34721022, 2021). "Taken together, we hypothesized that G-749 effectively reduced phosphorylation of STAT3 and AKT, which are involved in cell proliferation, through the reduction of TYRO3 in colon cancer cells." (PMID 34721022, 2021). "Interestingly, we found that TYRO3 protein levels decreased in a concentration-dependent manner when colon cancer cells were treated with G-749." (PMID 34721022, 2021). "MER and TYRO3 were expressed in all the colon cancer cell lines." (PMID 34721022, 2021). "However, our knockdown results revealed that TYRO3 is a more effective drug target than MER in colon cancer cells." (PMID 34721022, 2021). "Recent studies have indicated that TYRO3 could promote cell proliferation, invasion, and chemoresistance in several human cancers, including bladder cancer, colon cancer, and breast cancer." (PMID 32018224, 2020). "Moreover, disruption of the NLS altered cellular morphology and induced apoptosis and expression of nuclear-localized TYRO3 was a poor prognostic marker in colon cancer." (PMID 30501104, 2018).
colon cancer (continued). "Moreover, treatment with anti-TYRO3 antibody enhanced sensitivity to 5-fluorouracil in vivo in mice with a subcutaneous HCT-116 colon cancer xenograft." (PMID 30501104, 2018). "Expression of nuclear-localized TYRO3 was a poor prognostic marker in colon cancer." (PMID 30501104, 2018). "A fragment of TYRO3 that lacked the N-terminus was also detected in the nucleus in colon cancer cells and mutations in a putative nuclear localization signal (NLS) inhibited nuclear translocation." (PMID 30501104, 2018). "Our data showed that benzyl‐α‐GalNAc treatment decreased the molecular weight of TYRO3 and MERTK, suggesting that O‐glycans are also present in TYRO3 and MERTK in colon cancer cells." (PMID 36409270, 2023). "In this study, we demonstrated the potential of TYRO3 and MER as drug targets in colon cancer cells." (PMID 34721022, 2021). "To investigate the effect of siRNA targeting TYRO3, AXL and MER on signaling pathways, we analyzed the signaling pathways involved in cell proliferation by western blot analysis in colon cancer cells." (PMID 34721022, 2021). "The authors also observed that silencing TYRO3 in HCT116 and HT29 colon cancer cell lines reduced cell migration and invasion." (PMID 28727830, 2017). "Taken together, these results suggest that TYRO3 and MER may be drug targets for G-749 in colon cancer." (PMID 34721022, 2021). "To further investigate whether TAM RTKs can induce cell proliferation and apoptosis in colon cancer cells, we downregulated the expression of TAM RTKs using specific siRNAs targeting TYRO3, AXL and MER." (PMID 34721022, 2021). "Although TYRO3 expression was positively correlated with GLUT1 and GLUT3 expression in rectal cancer tissues, no such correlation could be observed with GLUT1, GLUT2, and GLUT3 expression in colon cancer tissues." (PMID 37116196, 2023).
rheumatoid arthritis (8 papers, 2011 to 2023). A chronic, systemic autoimmune disorder characterized by inflammation in the synovial membranes and articular surfaces. "Tyro3, Axl, and Mertk (abbreviated TAMs) comprise a family of homologous type 1 receptor tyrosine kinases (RTKs) that have been implicated as inhibitory receptors that dampen inflammation, but their roles in the pathogenesis of rheumatoid arthritis remains understudied." (PMID 37537628, 2023). "Our present results indicate that Axl and Mertk inhibit articular cartilage and bone damage by down-regulation selective cytokines in joint tissues while Tyro3 has an opposing function to affect the onset of rheumatoid arthritis." (PMID 37537628, 2023). "We also note that TYRO3 is targeted by an approved drug for rheumatoid arthritis, fostamatinib, highlighting an opportunity for the repurposing of fostamatinib to treat DKD." (PMID 36349687, 2023). "Another study detected increased TYRO3 expression by FACS analysis on the surface of pro-osteoclastogenic CD14+CD16− monocyte subpopulation in the blood of rheumatoid arthritis patients, indicating a role for TYRO3 in monocytic osteoclast precursor cells in the circulation." (PMID 38203403, 2023). "For example, loss of negative-regulatory receptor tyrosine kinases Tyro3, Axl, and Mer exacerbates lupus-like disease, rheumatoid arthritis, and inflammatory bowel disease through enhanced Toll-like receptor signaling." (PMID 26517880, 2015). "The objective of this study was to elucidate whether the plasma levels of soluble Mer (sMer) and Tyro3 (sTyro3) were increased in systemic lupus erythematosis (SLE), rheumatoid arthritis (RA), or critical limb ischemia (CLI)." (PMID 21496228, 2011).